TRIM50 (tripartite motif containing 50)
Description:
E3 ubiquitin-protein ligase that ubiquitinates Beclin-1/BECN1 in a 'Lys-63'-dependent manner enhancing its binding to ULK1. In turn, promotes starvation-induced autophagy activation. Also interacts with p62/SQSTM1 protein and thereby induces the formation and the autophagy clearance of aggresome-associated polyubiquitinated proteins through HDAC6 interaction. Also promotes NLRP3 inflammasome activation by directly inducing NLRP3 oligomerization independent of its E3 ligase function (By similarity).
Synonyms: TRIM50A; FLJ32804
Tractability: PROTAC: UniProt records ubiquitination sites on it.
Gene: Protein-coding gene on chromosome 7 (73,312,536 to 73,328,082, reverse strand). Ensembl gene ENSG00000146755.
Subcellular location: Cytoplasm
Subcellular location (Human Protein Atlas): Cytosol
Pathways (Reactome):
Immune System: Antigen processing: Ubiquitination & Proteasome degradation
Gene Ontology:
Molecular function: identical protein binding; protein binding; ubiquitin protein ligase activity; zinc ion binding
Biological process: innate immune response
Cellular component: cytoplasm
Genetic constraint (gnomAD): Loss-of-function variants: 34 observed, 42.31 expected, observed/expected ratio (o/e) 0.8, 90% interval 0.61 to 1.07. The upper end of that interval is the gene's LOEUF score, 1.07, which puts it in group 4 of 6, group 1 being the genes least tolerant of losing a copy. Missense variants: 633 observed, 627.32 expected, observed/expected ratio (o/e) 1.01, 90% interval 0.94 to 1.08. Synonymous variants: 307 observed, 274.96 expected, observed/expected ratio (o/e) 1.12, 90% interval 1.02 to 1.23.
Homologues: Orthologues: chimpanzee TRIM50 (99% identical), macaque TRIM50 (98% identical), pig TRIM50 (91% identical), guinea pig TRIM50 (90% identical), dog TRIM50 (89% identical), rabbit TRIM50 (89% identical), mouse Trim50 (88% identical), rat Trim50 (87% identical), tropical clawed frog trim50 (54% identical). Paralogues in human: TRIM73 (48% identical), TRIM74 (48% identical), TRIM39 (27% identical), TRIM72 (27% identical), TRIM27 (26% identical), TRIM69 (25% identical), MID1 (25% identical), TRIM58 (25% identical), TRIM7 (25% identical), TRIM11 (24% identical), TRIM21 (24% identical), TRIM41 (24% identical), and 68 more.
Diseases named in the same sentence as TRIM50 in open-access papers:
TRIM50 is named in the same sentence as 14 diseases in open-access papers, as found by Europe PMC text mining. Sharing a sentence is not in itself a finding about the gene and the disease. The quoted sentences say what the papers report.
gastric cancer (6 papers, 2022 to 2025). A primary or metastatic malignant neoplasm involving the stomach. "TRIM50 was under-expressed in gastric cancer tissues, which was associated with larger tumor size, advanced TNM stages, and poorer survival outcomes in clinical analysis." (PMID 39768197, 2024). "PGK1 is K48 ubiquitinated and degraded by TRIM50, which inhibits glycolysis and the malignant progression of gastric cancer." (PMID 41184227, 2025). "The differential expression of TRIM50 in the gastric cancer cell lines MKN-45 and HGC-27 facilitated our exploration of the biological functions of TRIM50." (PMID 38993561, 2024). "A recent study has also identified the inhibitory role of TRIM50 in the progression of gastric cancer." (PMID 38993561, 2024). "Furthermore, the downregulation of TRIM50 in gastric cancer cells was mediated by the METTL3/YTHDF2 axis via m6A methylation." (PMID 39768197, 2024).
hepatocellular carcinoma (5 papers, 2018 to 2024). A malignant tumor that arises from hepatocytes. "A similar result was obtained in hepatocellular carcinoma, which showed that TRIM50 directly binds with Snail1 for its K-48 linked ubiquitous degradation, thus reversing Snail1-mediated EMT process." (PMID 34568024, 2021). "Up to now, TRIM50 has only been shown to act as a tumor suppressor in hepatocellular carcinoma and ovarian cancer." (PMID 34568024, 2021). "TRIM50 had tumor suppressor activity in hepatocellular carcinoma (HCC) cells by directly targeting SNAIL and reversing EMT." (PMID 31823782, 2019). "However, the role of TRIM50 in hepatocellular carcinoma (HCC) remains to be clarified." (PMID 29789583, 2018).
pancreatic cancer (3 papers, 2021 to 2024). "Then, the association between TRIM50 expression and clinicopathological characteristics was analyzed in our cohort of pancreatic cancer tissues." (PMID 34568024, 2021). "In our present study, we found that the expression of TRIM50 was significantly downregulated in pancreatic cancer tissues, which was closely associated with tumor size, lymphatic metastasis, and TNM stage." (PMID 34568024, 2021). "We found that TRIM50 expression was significantly downregulated in pancreatic cancer tissues and negatively associated with malignant characteristics and clinical survival of pancreatic cancer patients." (PMID 34568024, 2021). "In this study, we first analyzed the expression pattern and clinical significance of TRIM50 in pancreatic cancer and found that TRIM50 expression is significantly reduced in pancreatic cancer tissues and its downregulation is associated with poor survival for pancreatic cancer patients." (PMID 34568024, 2021). "The results showed that rescue of TRIM50 significantly restored the decreased cell proliferation and invasion, and reversed EMT caused by TRIM50 depletion in PANC-1 and SW1990 cells, further confirming the requirement of TRIM50 in EMT-associated phenotypes of pancreatic cancer." (PMID 34568024, 2021). "Based on the study of TRIM50 in liver and pancreatic cancer, it was found that TRIM50 blocked EMT by targeting SNAI1 and down-regulating its expression." (PMID 39538371, 2024). "For example, TRIM50 can suppress pancreatic cancer progression and reverse EMT via Snail1, which is a key regulator of EMT." (PMID 36461099, 2022). "In summary, our study shows that decreased TRIM50 expression is positively correlated with malignant behaviors and predicts a poor prognosis in pancreatic cancer." (PMID 34568024, 2021). "TRIM50 overexpression inhibited pancreatic cancer cell migration and invasion, we explored the mechanisms associated with this change in phenotype." (PMID 34568024, 2021). "In our present study, we analyzed the expression and clinical significance of TRIM50 in pancreatic cancer and explored the roles of TRIM50 in the development and progression of pancreatic cancer." (PMID 34568024, 2021). "Altogether, these results show that TRIM50 suppresses cell migration and distant metastasis of pancreatic cancer." (PMID 34568024, 2021). "TRIM50 overexpression inhibited pancreatic cancer cell proliferation, migration, and invasion in vitro and suppressed pancreatic cancer growth and distant metastasis in vivo, while TRIM50 knockdown had the opposite effects in vitro." (PMID 34568024, 2021). "To corroborate the function of TRIM50 in pancreatic cancer metastasis further, we injected TRIM50-overexpressing BxPC-3 and vector control cells into the tail vein or spleen of nude mice." (PMID 34568024, 2021). "To investigate the expression pattern of TRIM50 in pancreatic cancer, we first analyzed the expression of TRIM50 at mRNA level in pancreatic cancer and normal tissues based on the data from GEO database." (PMID 34568024, 2021). "Correlations between TRIM50 expression and clinicopathologic parameters in pancreatic cancer patients." (PMID 34568024, 2021). "We found that E3 ubiquitin ligase TRIM50 interacted with Snail1, targeted it to ubiquitination and degradation, and finally destabilized it in pancreatic cancer." (PMID 34568024, 2021). "Simultaneously, nuclear TRIM50 was often observed in normal pancreas tissues, but rarely in pancreatic cancer tissues, suggesting possible different roles for TRIM50 under physiological and pathological conditions." (PMID 34568024, 2021). "TRIM50 expression was significantly decreased in pancreatic cancer tissues compared with normal pancreas tissues as revealed by multiple GEO datasets." (PMID 34568024, 2021). "In this study, we noticed that TRIM50 localized mainly in the cytoplasm of normal pancreas and pancreatic cancer tissues." (PMID 34568024, 2021).
pancreatic cancer (continued). "Our results also revealed low expression of TRIM50 (- or +) in the majority of pancreatic tumors examined, whereas high expression of TRIM50 (++ or +++) in the majority of nontumor specimens." (PMID 34568024, 2021). "Given that EMT is closely associated with tumor metastasis and that many members of the TRIM family, including TRIM50, participate in cancer progression via regulating EMT, we determined whether TRIM50 affects the EMT process of pancreatic cancer cells." (PMID 34568024, 2021). "Collectively, the results further confirm TRIM50 as an antioncogene in pancreatic cancer." (PMID 34568024, 2021). "To identify whether TRIM50 is involved in pancreatic cancer suppression, we firstly measured the expression of TRIM50 in human pancreatic cancer cell lines." (PMID 34568024, 2021). "The molecular mechanism by which TRIM50 inhibits pancreatic cancer growth warrants further study." (PMID 34568024, 2021). "Furthermore, pancreatic cancer patients with low TRIM50 expression had a worse prognosis than those with high TRIM50 expression." (PMID 34568024, 2021). "Furthermore, TRIM50 suppressed the malignant phenotypes of pancreatic cancer dependent on its inhibition of Snail1." (PMID 34568024, 2021). "In addition, depletion of TRIM50 further confirmed its anticarcinogenic effect in pancreatic cancer." (PMID 34568024, 2021). "However, the domains that mediate the interaction between TRIM50 and Snail1, as well as the ubiquitination sites and subcellular localization of Snail1 mediated by TRIM50 in pancreatic cancer warrant further investigations." (PMID 34568024, 2021). "Furthermore, we showed that TRIM50 inhibited pancreatic cancer invasiveness and distant metastasis and reversed the EMT process, which was supported by the roles of TRIM67 as tumor suppressor in breast cancer and lung cancer." (PMID 34568024, 2021). "Additionally, TRIM50 overexpression induced pancreatic cancer cell apoptosis shown by flow cytometry analysis, which may be a reason for decreased tumor growth." (PMID 34568024, 2021). "The findings suggest that TRIM50 may exert antioncogenic roles in pancreatic cancer." (PMID 34568024, 2021). "Taken together, these data suggest that TRIM50 may act as a tumor suppressor in pancreatic cancer." (PMID 34568024, 2021). "Functionally, TRIM50 overexpression in pancreatic cancer cells decreases their proliferation and motility capabilities and reverses the epithelial-mesenchymal transition (EMT) process, whereas TRIM50 depletion had the opposite effects." (PMID 34568024, 2021). "However, the expression pattern and role of TRIM50 in pancreatic cancer remains unknown." (PMID 34568024, 2021). "In conclusion, our findings identify TRIM50 as a tumor suppressor that inhibits pancreatic cancer progression and reverses EMT via degrading Snail1 and provide new insights into the progression of pancreatic cancer." (PMID 34568024, 2021). "Furthermore, we evaluated the prognostic significance of TRIM50 expression in GSE57495 dataset and our cohort, both of which showed that pancreatic cancer patients with high TRIM50 expression had more favorable prognosis than those with low TRIM50 expression." (PMID 34568024, 2021). "However, critical regulators of TRIM50 expression in pancreatic cancer are not involved in our study, which needs to be studied further." (PMID 34568024, 2021).
Williams-Beuren syndrome (3 papers, 2011 to 2021). "TRIM50 is one of 28 hemizygous genes mapping to the region rearranged in Williams Beuren syndrome (WBS), a genomic disorder characterized by mental retardation and multiple dysmorphic and metabolic features." (PMID 22792322, 2012). "Unequal crossing-over and aberrant homologous recombination between the tandem segments that contain TRIM50, TRIM73, and TRIM74 causes Williams-Beuren syndrome in 1/7,500 to 1/25,000 newborns." (PMID 22144910, 2011). "Tripartite motif-containing protein 50 (TRIM50), as a member of the TRIM family, was first identified as an E3 ubiquitin ligase in Williams-Beuren syndrome and reported to promote the formation of sophisticated canaliculi and microvilli during acid secretion in parietal cells." (PMID 34568024, 2021).
breast carcinoma (2 papers, 2021 to 2024). "In this study, we demonstrate that TRIM50 is downregulated in human breast cancer and that its overexpression closely correlates with diminished invasion capacity in breast cancer, suggesting that TRIM50 may serve as a diagnostic marker and therapeutic target." (PMID 39538371, 2024). "Together, our findings presented a potential therapeutic target and prognostic indicator of TRIM50 in breast cancer." (PMID 39538371, 2024). "We interrogated the differentially expressed genes in the Gene Expression Omnibus (GEO) database and discovered a novel TRIM member, namely TRIM50, which is down-regulated in breast cancer." (PMID 39538371, 2024). "We overexpressed TRIM50 in triple-negative breast cancer cell lines using plasmid and found that TRIM50 upregulation markedly reduced breast cancer cell proliferation, clone formation, and migration, as well as promoted breast cancer cell apoptosis." (PMID 39538371, 2024). "In the present study, we first investigated the public database to present the potential role of TRIM50 in breast cancer." (PMID 39538371, 2024). "Compared with mRNA levels of TRIM50 in 45 pairs of breast cancer, TRIM50 levels in adjacent breast tissues were significantly higher (Luminal:N = 31, p < .01; Her2:N = 9, p < .001; TNBC:N = 5, p < .0001)." (PMID 39538371, 2024). "TRIM50 plays a key role in breast cancer proliferation and potentially serves as a prognostic and therapeutic target." (PMID 39538371, 2024). "TRIM50 is overexpressed in many cancers, although few studies focused on TRIM50‘s role in breast cancer." (PMID 39538371, 2024). "To verify the effect of TRIM50 on the biological behavior of breast cancer cells, we carried out a series of experiments (CCK-8, clone formation, flow cytometry, cell scratch, and Transwell experiment)." (PMID 39538371, 2024). "Herein, our present study anatomized the clinical value of TRIM50 in breast cancer by bioinformatics, cell experiments, and in vivo xenograft experiments." (PMID 39538371, 2024). "Besides, TRIM50 expression is lower in breast cancer than in normal mammary tissue with a statistically significant difference." (PMID 39538371, 2024). "Analysis of immunohistochemical staining under optical microscopes revealed that TRIM50 was significantly diminished in luminal, HER2-positive breast cancer, and TNBC than in normal breast tissues." (PMID 39538371, 2024). "First, this study only preliminarily confirmed that TRIM50 was adversely correlated with the nuclear expression of the transcription factor SNAI1 and has not fully elucidated the regulatory mechanism of TRIM50 on SNAI1 in breast cancer." (PMID 39538371, 2024).
ovarian carcinoma (2 papers, 2024). A malignant neoplasm originating from the surface ovarian epithelium. "In ovarian cancer, TRIM50 has been found to act as a negative regulator of Src protein, promoting ubiquitin-dependent K48-linked ubiquitination and the subsequent degradation of Src, thereby inhibiting ovarian cancer development." (PMID 38993561, 2024).
liver cancer (1 paper, 2018). An epithelial or non-epithelial malignant neoplasm that arises from the liver. "In this study, we identified SNAIL as a novel binding partner of TRIM50 in liver cancer cells." (PMID 29789583, 2018). "Altogether, this study provided clues to understand the pathogenesis of HCC, and it indicated that therapeutic strategy by upregulating TRIM50 in SNAIL overexpressed cancers may pave a new avenue for manipulating liver cancer." (PMID 29789583, 2018). "Further assay of western blot data showed that patients with advanced Tumor Lymph Node Metastasis stages (TNM stages), Barcelona Clinic Liver Cancer stages (BCLC stages) and metastasis were prone to have lower levels of TRIM50 expression." (PMID 29789583, 2018). "Here we showed that TRIM50 expression was significantly decreased in liver cancer tissues compared with corresponding non-cancerous liver tissues, and its decreased expression was significantly correlated with advanced disease progression." (PMID 29789583, 2018). "We first detected TRIM50 expression by IHC in HCC tissues and corresponding non-cancerous liver tissues from 79 clinical HCC patients, and our data showed that TRIM50 expression was significantly decreased in the liver cancer tissues compared with corresponding distal non-cancerous liver tissues." (PMID 29789583, 2018).
lymph node metastasis (1 paper, 2024). "The further local cohort-based clinicopathological association analysis verified that lower TRIM50 expression was related to lymph node metastasis (p = .004) and advanced TNM stage (p = .019), irrelevant to ER as well as HER2." (PMID 39538371, 2024). "Besides, the correlation analysis showed that TRIM50 overexpression was significantly correlated with lymph node metastasis and senior clinical stage." (PMID 39538371, 2024).
neuroblastoma (1 paper, 2012). Neuroblastoma (NB) is the most common solid, extracranial childhood tumor. "To rule out that the observed pattern was due to TRIM50 overexpression, we showed that also the endogenous TRIM50 localizes in diffuse cytoplasmic round bodies in human neuroblastoma-derived SH-SY5Y cell lines." (PMID 22792322, 2012).
oral squamous cell carcinoma (1 paper, 2022). "For example, the TRIM50 could enhance the proliferation, cloning, invasion and migration abilities of oral squamous cell carcinoma by reducing the expression level of retinoblastoma tumor suppressor protein (Rb)." (PMID 35668376, 2022).